RNU6-66P (RNA, U6 small nuclear 66, pseudogene)
Synonyms: RNU6-66
Gene: Small nuclear RNA gene on chromosome 13 (73,112,915 to 73,113,018, reverse strand). Ensembl gene ENSG00000200267.
Homologues: Orthologues: chimpanzee U6 (98% identical), macaque U6 (88% identical). Paralogues in human: RNU6-1331P (91% identical), RNU6-1088P (89% identical), RNU6-189P (89% identical), RNU6-23P (88% identical), RNU6-242P (88% identical), RNU6-774P (88% identical), RNU6-1094P (88% identical), RNU6-11P (88% identical), RNU6-33P (88% identical), RNU6-37P (88% identical), RNU6-47P (88% identical), RNU6-7 (88% identical), and 1284 more.